LYRM9 (LYR motif containing 9)
Synonyms: C17orf108; HSD24
Tractability: No criterion of Open Targets' tractability assessment is met for any kind of drug.
Gene: Protein-coding gene on chromosome 17 (27,878,314 to 27,894,752, reverse strand). Ensembl gene ENSG00000232859.
Gene Ontology:
Cellular component: mitochondrion
Genetic constraint (gnomAD): Loss-of-function variants: 14 observed, 9.51 expected, observed/expected ratio (o/e) 1.47, 90% interval 0.95 to 1.92. That is too few expected variants to judge how well the gene tolerates losing a copy. Missense variants: 94 observed, 85.64 expected, observed/expected ratio (o/e) 1.1, 90% interval 0.93 to 1.3. Synonymous variants: 42 observed, 33.24 expected, observed/expected ratio (o/e) 1.26, 90% interval 0.99 to 1.63.
Homologues: Orthologues: chimpanzee LYRM9 (94% identical), dog LYRM9 (91% identical), mouse Lyrm9 (91% identical), rat Lyrm9 (91% identical), pig LYRM9 (90% identical), guinea pig LYRM9 (88% identical), zebrafish lyrm9 (64% identical).
Diseases named in the same sentence as LYRM9 in open-access papers:
LYRM9 is named in the same sentence as 1 disease in open-access papers, as found by Europe PMC text mining. Sharing a sentence is not in itself a finding about the gene and the disease. The quoted sentences say what the papers report.
cancer (1 paper, 2020). A tumor composed of atypical neoplastic, often pleomorphic cells that invade other tissues. "A total of 10 genes that were disrupted or within breakpoint‐associated TAD structures were classified as known (FHIT, FLCN, NCOA4, and RET) or candidate cancer genes (LLGL1, LRIG1, LYRM9, RASGEF1A, ST3GAL6, and TMEM199)." (PMID 31943436, 2020). "Analysis demonstrated two known cancer genes (NCOA4 and RET) and a further five candidate cancer genes (LLGL1, LRIG1, LYRM9, ST3GAL6, and TMEM199) were within breakpoint‐containing TADs." (PMID 31943436, 2020).